LTB4R (leukotriene B4 receptor)
Description:
Receptor for extracellular ATP > UTP and ADP. The activity of this receptor is mediated by G proteins which activate a phosphatidylinositol-calcium second messenger system. May be the cardiac P2Y receptor involved in the regulation of cardiac muscle contraction through modulation of L-type calcium currents. Is a receptor for leukotriene B4, a potent chemoattractant involved in inflammation and immune response.
Synonyms: P2Y7; BLT1; BLTR; CMKRL1; GPR16; P2RY7; LTB4R1; LTBR1
Tractability: Small molecule: a drug acting on it is in phase 2 or 3 trials; a structure with a bound ligand is known; a high-quality ligand is known; it belongs to a druggable protein family. Antibody: its Gene Ontology location is reachable by antibodies, with high confidence; UniProt places it where antibodies can reach, with medium confidence; UniProt predicts a signal peptide or a membrane-spanning region. PROTAC: a small molecule that binds it is known. Other modalities: a drug acting on it is in phase 2 or 3 trials.
Target class: Leukotriene receptor; Small molecule receptor (family A GPCR); Membrane receptor; Lipid-like ligand receptor (family A GPCR); Family A G protein-coupled receptor
Chemical probes: AMELUBANT (high quality), BIIL 315 (high quality), SC 50605
Gene: Protein-coding gene on chromosome 14 (24,311,450 to 24,318,036, forward strand). Ensembl gene ENSG00000213903.
Subcellular location: Cell membrane
Pathways (Reactome):
Signal Transduction: G alpha (q) signalling events; Leukotriene receptors
Gene Ontology:
Molecular function: G protein-coupled peptide receptor activity; leukotriene B4 receptor activity; leukotriene receptor activity; nucleotide binding; G protein-coupled receptor activity
Biological process: G protein-coupled receptor signaling pathway; immune response; inflammatory response; muscle contraction; neuropeptide signaling pathway; phospholipase C-activating G protein-coupled receptor signaling pathway; leukotriene signaling pathway
Cellular component: plasma membrane; membrane
Genetic constraint (gnomAD): Loss-of-function variants: 1 observed, 0.56 expected, observed/expected ratio (o/e) 1.78, 90% interval 0.33 to 1.92. That is too few expected variants to judge how well the gene tolerates losing a copy. Missense variants: 470 observed, 444.6 expected, observed/expected ratio (o/e) 1.06, 90% interval 0.98 to 1.14. Synonymous variants: 250 observed, 208.23 expected, observed/expected ratio (o/e) 1.2, 90% interval 1.08 to 1.33.
Homologues: Orthologues: chimpanzee LTB4R (99% identical), macaque LTB4R (92% identical), pig LTB4R (81% identical), rabbit LTB4R (78% identical), rat Ltb4r (78% identical), dog LTB4R (74% identical), guinea pig LTB4R (72% identical), tropical clawed frog ltb4r (43% identical), zebrafish ltb4r (39% identical), Drosophila melanogaster Rh7 (22% identical), Caenorhabditis elegans trhr-1 (17% identical). Paralogues in human: LTB4R2 (37% identical), PTGDR2 (25% identical), SSTR5 (25% identical), SSTR3 (25% identical), UTS2R (24% identical), OPRK1 (23% identical), OPRL1 (23% identical), OPRD1 (23% identical), SSTR1 (22% identical), OPRM1 (22% identical), SSTR4 (22% identical), CMKLR2 (22% identical), and 5 more.
Diseases named in the same sentence as LTB4R in open-access papers:
LTB4R is named in the same sentence as 113 diseases in open-access papers, as found by Europe PMC text mining. Sharing a sentence is not in itself a finding about the gene and the disease. The quoted sentences say what the papers report.
asthma (18 papers, 2010 to 2023). "LTB4R has been linked to a variety of inflammatory diseases such as asthma, allergic airway inflammation, inflammatory arthritis, atherosclerosis, inflammatory bowel disease and psoriasis." (PMID 37697338, 2023). "This study represents the first characterisation of the LTB4R locus with respect to gene structure in the lung and the first evaluation of LTB4R SNPs for association with asthma susceptibility and severity." (PMID 23167751, 2012). "Our study represents the first characterisation of the LTB4R locus with respect to gene structure in the lung and the first study to investigate association of LTB4R SNPs with asthma and importantly asthma severity where LTB4 has been suggested to have a more prominent role." (PMID 23167751, 2012). "Six LTB4R single nucleotide polymorphisms (SNPs) were genotyped in 370 Caucasian asthma families and 299 Adult Asthma Individuals (n=1877 total) and were evaluated for association with asthma and severity (BTS) outcome measures using Family Based Association Test, linear regression and chi square." (PMID 23167751, 2012). "BLT2 is a low-affinity leukotriene B4 receptor that plays an essential role in the pathogenesis of various inflammatory diseases, including asthma and cancer." (PMID 37954206, 2023). "DMR analysis implicated genes with previously reported links to schizophrenia (LAX1), skin disorders (PSORS1C, LTB4R), and airway inflammation including asthma (LTB4R), present only at birth in the higher latitudes (≥ 50°N)." (PMID 37697338, 2023). "Proinflammatory signaling initiated by leukotriene LTB4 through its BLT1 and BLT2 receptors (encoded by LTB4R and LTB4R2 genes) is associated with various diseases, such as asthma, rheumatoid arthritis, atherosclerosis, abdominal aortic aneurysm, multiple sclerosis, and cancer." (PMID 33335138, 2020). "This study does not provide evidence supporting a role for LTB4R SNPs in susceptibility to develop asthma or severity phenotypes using asthma enriched families and adult asthma subjects." (PMID 23167751, 2012). "LTB4R polymorphisms do not appear to be susceptibility markers for the development of asthma in Caucasian subjects." (PMID 23167751, 2012). "Our data indicate no LTB4R SNPs tested were associated with asthma diagnosis, FEV1 or severity (BTS) in the families." (PMID 23167751, 2012). "Therefore, LTA4H inhibitors, 5-Lipoxygenase Activating Protein inhibitors and Leukotriene-B4 receptor antagonists might represent a potential therapeutic strategy that could modulate key aspects of early-onset asthma." (PMID 34550981, 2021). "Blockade of leukotriene B4 receptor 1 (BLT1)/BLT2 by antagonists can reduce neutrophil infiltration based on findings in an HDM- and LPS-induced mouse asthma model." (PMID 35626330, 2022). "Our data suggest that LTB4R1 and LTB4R2 have complicated gene structure and are polymorphic and that polymorphisms spanning the LTB4R locus are not determinants of asthma susceptibility." (PMID 23167751, 2012). "While no other study has assessed the role of LTB4R SNPs in asthma-related traits, research has involved SNPs spanning these genes in the cardiovascular field, where leukotrienes have also been shown to contribute to early atherosclerosis." (PMID 23167751, 2012). "Our studies did not observe any significant association with asthma, FEV1 or severity (BTS defined) in the asthma families or adult asthmatics for any LTB4R SNP analysed." (PMID 23167751, 2012).
atherosclerosis (12 papers, 2012 to 2024). A disease characterized by the build-up of fatty material and calcium deposition in the arterial wall resulting in partial or complete occlusion of the arterial lumen. "BLT1 (LTB4R) is also an attractive drug target for allergic airway inflammation, inflammatory arthritis, atherosclerosis, and psoriasis." (PMID 36429034, 2022).
Insulin resistance (11 papers, 2013 to 2022). Increased resistance towards insulin, that is, diminished effectiveness of insulin in reducing blood glucose levels. "The ZS-Ag-NPs treatment significantly decreased insulin resistance and metabolic inflammation-related LTB4-R, TNF-α, IL-4 and STAT-6 mRNA levels." (PMID 34685001, 2021).
Obesity (10 papers, 2013 to 2025). Accumulation of substantial excess body fat. "The role of BLT-1 (leukotriene B4 receptor) in promoting trafficking of monocyte to adipose tissue and chronic inflammation in obesity has also been elucidated." (PMID 36994095, 2023). "B-cell localisation around macrophage clusters may be central to their functional relevance within adipose tissue in obesity, suggesting a role in steering macrophage functionality, perhaps via LTB4/leukotriene-B4 receptor 1 (LTB4R1) signalling." (PMID 29479350, 2018).
psoriasis (9 papers, 2015 to 2025). An autoimmune condition characterized by red, well-delineated plaques with silvery scales that are usually on the extensor surfaces and scalp. "CTSB, JAK1, and LTB4R were the only genes found by random forest analysis to be significant indicators of the psoriasis condition in both the whole skin datasets and isolated MCs." (PMID 37681909, 2023). "To ensure the human relevance, we examined the mRNA expressions of LTA4H, ALOX5, and LTB4R (a human LTB4 receptor) in human psoriasis lesions, using a public microarray data set23." (PMID 30089836, 2018).
pancreatic cancer (6 papers, 2008 to 2024). "An up-regulation of LTB4R protein has been reported in gastric and pancreatic cancer as well." (PMID 27475906, 2016). "However, combining the LTB4R antagonist LY293111 to gemcitabine did not add any benefit in terms of survival to chemotherapy-naïve patients with advanced pancreatic carcinoma." (PMID 27475906, 2016).
Arthritis (5 papers, 2012 to 2021). Inflammation of a joint. "In this regard, a sequential role for the leukotriene B4 receptor Blt1, Ccr1 and Cxcr2 has previously been reported for neutrophil recruitment in a mouse model of arthritis." (PMID 22916017, 2012).
breast carcinoma (5 papers, 2015 to 2025). "Given that aberrant apoptotic mechanisms are often linked to chemo-resistance, targeting LTB4R could lead to novel intervention strategies applicable beyond CRC to other malignancies like ovarian and breast cancers." (PMID 38259082, 2024). "We analyzed the TCGA BC expression dataset by dichotomizing the RNA-seq gene expression data using maximally selected rank statistics for determining the optimal threshold in order to assess the association of LTB4R and LTB4R2 expression levels with breast cancer patient survival." (PMID 38139172, 2023). "Expression of LTB4R was essential for CD8+ T cell infiltration into tumours and invasiveness of ovarian cancer cells and breast cancer cells was increased by MMP-2 pathways and IL-8 pathway respectively." (PMID 34229684, 2021). "Pan-cancer bioinformatic analysis revealed that higher LTB4R expression was associated with poor relapse-free survival (RFS), poor OS, and poor distant metastasis-free survival (DMFS) in breast cancer datasets without segregation into molecular subtypes." (PMID 38139172, 2023). "Among the features discriminating a moderately methylated triple negative breast cancer subtype (modTNBC) from all other BC methylotypes is the hypomethylation of a CpG island belonging to the leukotriene receptor 1 gene LTB4R and the leukotriene receptor 2 gene LTB4R2." (PMID 38139172, 2023).
Sepsis (5 papers, 2017 to 2023). Sepsis is defined as life-threatening organ dysfunction caused by a dysregulated host response to infection. "The potent chemoattractant and proinflammatory mediator LTB4 is synthesized from arachidonic acid by ALOX5.Multiple risk factors for ARC such as trauma, sepsis, cancer, etc., also found differences in LTB4R expression." (PMID 37445637, 2023). "Moreover, LTB4R was found to be associated with mortality of sepsis patients." (PMID 37033939, 2023). "Patients with higher risk scores tended to express lower levels of LTB4R, HLA-DMB and IL4R, indicating that upregulation of the three IRGs was a favorable prognostic factor in sepsis." (PMID 37033939, 2023). "Compared with healthy controls (n = 42), IL4R and LTB4R were significantly upregulated in sepsis patients (n = 479), while HLA-DMB was significantly downregulated (all P < 0.001)." (PMID 37033939, 2023). "The qPCR data exhibited the same pattern of expression of these genes as the GSE65682 dataset, with IL4R and LTB4R being expressed at significantly higher levels in sepsis cases and HLA-DMB exhibiting the opposite trend (all P < 0.01)." (PMID 37033939, 2023). "LTB4R (Cytokines and leukotriene B4 receptor) was viewed as pro-inflammatory mediators, and its down-regulated expression could attenuate microcirculation impairment during sepsis." (PMID 33949285, 2021). "LTB4/LTB4R pathway was also enriched in the pathogenesis of the sepsis." (PMID 33949285, 2021). "Additionally, leukocyte recruitment mediated by LTB4 and leukotriene B4 receptor type 1 (BLT1) plays an important role during sepsis." (PMID 28290498, 2017).
clear cell renal cell carcinoma (4 papers, 2021 to 2023). "In summary, our experimental results consistently suggest that high expression of LTB4R can be an independent risk factor for renal clear cell carcinoma." (PMID 36429034, 2022). "First, a CCK8 assay was performed to verify LTB4R’s effect on the proliferation viability of renal clear cell carcinoma cells." (PMID 36429034, 2022). "Flow cytometry validated LTB4R’s effect on renal clear cell carcinoma cells’ apoptosis and cell cycle." (PMID 36429034, 2022). "Scratch and transwell assays verified LTB4R’s effect on the migration and invasion ability of renal clear cell carcinoma cells." (PMID 36429034, 2022). "LTB4R plays an oncogenic role in renal clear cell carcinoma; it is expected to be a molecular target for renal clear cell carcinoma treatment and a predictive biomarker for prognosis." (PMID 36429034, 2022). "In addition, we found that LTB4R regulated the proliferation and apoptosis of renal clear cell carcinoma cells by regulating the AKT/mTOR signaling pathway’s phosphorylation process." (PMID 36429034, 2022). "Therefore, based on our previous studies, we further investigated LTB4R’s biological functions and mechanisms in the development of renal clear cell carcinoma." (PMID 36429034, 2022). "This study was conducted to investigate LTB4R’s action mechanism in renal clear cell carcinoma." (PMID 36429034, 2022). "Therefore, LTB4R has promise as a novel prognostic biomarker for renal clear cell carcinoma." (PMID 36429034, 2022). "A Western blot assay was conducted to further investigate LTB4R’s effect on apoptosis, cell cycle, EMT process, and AKT/mTOR signaling pathway in renal clear cell carcinoma at the protein level." (PMID 36429034, 2022). "Functionally, LTB4R promotes the migration, invasion, proliferation, and apoptosis of renal cancer cells; mechanistically, LTB4R influences the progression of renal clear cell carcinoma by regulating the AKT/mTOR signaling pathway and, thus, the development of renal clear cell carcinoma." (PMID 36429034, 2022). "To verify the relationship between LTB4R and the AKT/mTOR signaling pathway in renal clear cell carcinoma, we performed a Western blot assay and found that LTB4R positively regulates the AKT/mTOR pathway, affecting the development of renal clear cell carcinoma." (PMID 36429034, 2022).
colitis (4 papers, 2007 to 2025). Inflammation of the colon. "In humans, RvE1 selectively interacts with both the leukotriene B4 receptor (BLT1) and the G-protein coupled receptor ChemR23 expressed on the surface of neutrophils to promote the resolution of dermal inflammation, peritonitis and colitis in murine models of these diseases." (PMID 18091990, 2007).
lung carcinoma (3 papers, 2020 to 2025). "The identification of LTB4R, LTBP4, MPI, and TCN2, in conjunction with PSMA4, highlights the intricate heterogeneity of lung cancer and underscores the necessity for tailored therapeutic strategies." (PMID 39529882, 2024). "Next, we determined the expression levels of P2X sub-families P2RX1–7 and P2Y receptors P2RY1, P2RY2, P2RY4, P2RY5 (LPAR6), P2RY6, P2RY7 (LTB4R), P2RY8, P2RY9 (LPAR4), P2RY10–14 in normal lung tissues and lung cancer tissues." (PMID 32638267, 2020).
cardioembolic stroke (2 papers, 2012 to 2020). "The genetic variant of the leukotriene B4 receptor complex was shown to affect the risk of cardioembolic stroke." (PMID 32717948, 2020).
diabetes (2 papers, 2018 to 2020). "When only Group A and Group B were considered, the differences in the expressions of ALOX5, LTB4R, DDOST, and SIRT1 mRNAs were maintained after adjustment for sex, age, diabetes duration, and use of ACEI, ARB, and statin (P < 0.0001 for all genes)." (PMID 32273829, 2020).
injury (2 papers, 2016 to 2021). Damage inflicted on the body as the direct or indirect result of an external force, with or without disruption of structural continuity. "Blocking the leukotriene B4 receptor 1(LTB4R1) resulted in the decreased PMN rM into the circulation and alleviated the severity of acute lung injury." (PMID 33790916, 2021).
renal carcinoma (2 papers, 2021 to 2022). A carcinoma arising from the epithelium of the renal parenchyma or the renal pelvis. "Our results reveal that LTB4R is an important renal cancer biomarker and may be a highly specific therapeutic target." (PMID 36429034, 2022).
acute kidney injury (1 paper, 2019). Sudden and sustained deterioration of the kidney function characterized by decreased glomerular filtration rate, increased serum creatinine or oliguria. "Moreover, the LTB4-leukotriene B4 receptor 1 (BLT1) axis participates in the acute kidney injury via mediating the recruitment of renal neutrophils." (PMID 31357612, 2019).
acute lung injury (1 paper, 2015). A condition of lung damage that is characterized by bilateral pulmonary infiltrates (pulmonary edema) rich in neutrophils, and in the absence of clinical heart failure. "In mice and patients with acute lung injury (ALI), the alveolar recruitment of Treg cells, specifically mediated by leukotriene B4 (LTB4)-leukotriene B4 Receptor (BLT1) pathway, contribute to the resolution of lung inflammation, particularly in the resolution of ALI fibroproliferation." (PMID 25887535, 2015).
colorectal adenocarcinoma (1 paper, 2024). The most common type of colorectal carcinoma. "Using bioinformatics analysis of the GSE164191 and the Cancer Genome Atlas-colorectal adenocarcinoma (TCGA-COAD) datasets, we identified LTB4R as a hub gene influencing CRC prognosis." (PMID 38259082, 2024).
esophageal cancer (1 paper, 2016). A primary or metastatic malignant neoplasm involving the esophagus. "Up-regulation of LTB4R and down-regulation of CYSLTR2 gene expression may occur already in normal squamous esophageal epithelium of patients with esophageal cancer suggesting a potential role of these receptors in early steps of esophageal carcinogenesis." (PMID 27475906, 2016).
esophageal squamous cell carcinoma (1 paper, 2016). Esophageal squamous cell carcinoma (ESCC) is a type of esophageal carcinoma (EC) that can affect any part of the esophagus, but is usually located in the upper or middle third. "Expression of LTB4R, LTB4R2, CYSLTR1 and CYSLTR2 was analyzed by immunohistochemistry (IHC) and quantitative reverse transcription-polymerase chain reaction (qRT-PCR) in biopsy samples of 19 patients with esophageal squamous cell cancer and 9 sex- and age-matched patients with functional dyspepsia." (PMID 27475906, 2016). "We aimed to investigate the expression of LTB4R, LTB4R2, CYSLTR1 and CYSLTR2 in esophageal squamous cell carcinoma and adjacent non-transformed squamous epithelium of the esophagus, as well as in control biopsy samples from esophageal squamous epithelium of patients with functional dyspepsia." (PMID 27475906, 2016).
Hypertension (1 paper, 2024). The presence of chronic increased pressure in the systemic arterial system. "However, during hypertension onset at 10 weeks and robust hypertension at 16 weeks, the inflammatory markers Tnf, Il1b, Ccr1, Ccr5, Ilrn, and Ltb4r are statistically significantly upregulated in the kidney of female SHR vs WKY control." (PMID 39514592, 2024).
metastatic disease (1 paper, 2021). "However, in subsequent metastatic disease (Mets2), methylation decreased to lower levels for the specific DMRs identified (which included probes for DAXX, LTB4R & CIDEB) in both cases." (PMID 33436720, 2021).